SCARNA21B (small Cajal body-specific RNA 21B)
Gene: Small Cajal body-specific RNA gene on chromosome 1 (15,542,165 to 15,542,304, forward strand). Ensembl gene ENSG00000251866.
Gene Ontology:
Biological process: RNA processing
Cellular component: Cajal body; nucleolus